CDK2 (cyclin dependent kinase 2)
Diseases named in the same sentence as CDK2 in open-access papers (continued):
Sharing a sentence is not in itself a finding about the gene and the disease.
tumor (continued). "Results from our analysis also indicate that, among the thirty genes which are differentially expressed in OSCCs, seven of them (namely BRCA1, CCNE2, CDC25C, CDK1, CDK2, E2F1, and FANCD2) positively correlate with both tumor grade and HPV infection." (PMID 36768994, 2023). "Because HR impairment is synthetically lethal with PARP inhibition we reasoned that a CDK2 inhibitor, in combination with a PARP inhibitor should show greater anti-tumor activity compared to single agent." (PMID 37519629, 2023). "The upstream inhibitor of CDK2, CVT-313, reprogrammed the tumor microenvironment and reduced anti-PD-1 resistance." (PMID 37865750, 2023). "The expression level of cell cycle‐related proteins, such as cyclin D1, cyclin E, Cdk2, Cdk4, Cdk6, and PCNA was also decreased in anti‐Chi3L1 antibody‐treated lung metastasis tumor tissue." (PMID 34861103, 2022). "Here, β-carboline-3-carboxylic acid dimers also inhibited the expression of CDK2 and PLK which are involved in tumor immunity and pathogenesis, showing the broad-spectrum mechanism of carboline in arresting the cell cycle of tumor cells." (PMID 36325324, 2022). "YTHDF1 deficiency regulates the transformation efficiency of cyclin-dependent kinase 2 (CDK2), cyclin-dependent kinase 4 (CDK4), and cyclin D1 (CCND1) through the Keap1-Nrf2-AKR1C1 pathway to inhibit tumour cell proliferation and xenograft tumorigenesis." (PMID 35518355, 2022). "Shikonin arrests the cycle of tumor cells by regulating the expression of cycle-related proteins, such as cyclin A, cyclin B, CDK1, and CDK2." (PMID 35847368, 2022). "RB1, as a tumor suppressor, canonically regulates cell cycle progression and represents a downstream target for CDK4/6 or CDK2 inhibitors that are in clinical use." (PMID 36082941, 2022). "Our analysis of GBM datasets highlighted elevated yet heterogeneous expression of CDK2, 7 and 9 in GBM patient tumours, across all subtypes (classical, mesenchymal, proneural)." (PMID 34344865, 2021). "Decreased the protein expression of CDK2, CDK4, cyclin E, and Bcl-2 and increased the expression of CDKN1BElevated the ratio of LC3-II/LC3-I.Decreased tumor size and weight." (PMID 34026649, 2021). "We investigated a potential relationship between the histological HCC grade (serving as a measure for differentiation status and malignancy of tumours) and the level of CCNE1 and CDK2 expression." (PMID 34830835, 2021). "Inhibiting or downregulating the expression of CDK2 and CDK4 delays or inhibits cell cycle progression and reduces tumor proliferation and metastasis." (PMID 34582363, 2021). "The CDK2, 7 and 9 genes are frequently upregulated in GBM patients compared to non-tumour tissue and thus establishes a therapeutic rationale for targeting these CDKs specifically, using transcriptional CDK inhibitors, CYC065 (CDK2/9i) and THZ1 (CDK7i)." (PMID 34066147, 2021). "We found that CDK2, CDK4, CDK6, and STAT3 expressions were higher in tumor cohorts compared to normal cohorts." (PMID 33668805, 2021). "Meanwhile, the expression of cell cycle-related genes such as E2F1, Cyclin D1, Cyclin B1, and CDK2 was also decreased after ITPR3 knockdown while P21, as a classical tumor suppressor gene was upregulated." (PMID 33573671, 2021). "We characterized the kinase-signaling network, where we identified LCK and EGFR as interconnected, down-regulated kinases and the tumor suppressors ATM and CDK2 as interconnected, up-regulated kinases." (PMID 34238254, 2021). "It was important to note that combination of CDK2 inhibitor (K03861) and paclitaxel, the first-line chemotherapeutic drug of TNBC, resulted in synergistic tumor growth inhibition of TNBC cells." (PMID 33541412, 2021).
tumor (continued). "According to our anti-tumor drug resistance research findings, the IC50 of four drugs (Axitinib, SB216763, KU-55933, BMS-536924) were positive with expression of CDK2." (PMID 34409029, 2021). "In conclusion, our study identified CDK2 related immune forecast model, Nomogram model, forest map, ceRNA network, IC50 of anti-tumor drugs, to predict the prognosis and guide targeted therapy for LUAD patients." (PMID 34409029, 2021). "For instance, we have reported that KLF10 was phosphorylated by CDK2 and Raf-1 at Ser206 and Thr93, respectively, further affecting the role of KLF10 in tumor suppression." (PMID 34869587, 2021). "The results of the present study show that compared to Avastin treatment alone, combination treatment with FO and Se exerted a greater decrease in nuclear cyclin D1/E and CDK-2,4,-6 in TNBC tumor tissues." (PMID 33805447, 2021). "Western blot analysis of tumor homogenates also showed downregulation of NRP-1, cyclin E, CDK2 and N-cadherin, and upregulation of p27 and E-cadherin in miR-124-3p mimics-treated tumors." (PMID 33912463, 2021). "Analysis of the TCGA database revealed mRNA overexpression and copy number gain of CDK2, 5 and 9 in CCA tumor samples." (PMID 33116269, 2020). "Seliciclib, a first generation aminopurine inhibitor of CDK2, CDK7 and CDK9, has shown anti-proliferative activity in tumor cell lines and xenografts." (PMID 32645016, 2020). "Most of these genes (STAT5B, CDK6, CDK2, CDKN1B, E2F8, and E2F1) showed high mRNA expression in tumor tissues compared to adjacent non-tumor tissues." (PMID 32807134, 2020). "In fact, PLK1, CDK1, and AURKB were significantly upregulated in tumor tissues, by contrast, ATM was markedly downregulated expressed in tumor tissues, except CDK2." (PMID 33292231, 2020). "Seliciclib is an ATP competitive inhibitor of CDK2, CDK7 and CDK9, with an average anti-proliferative activity (IC50) in tumor cells of around 15 μM." (PMID 32645016, 2020). "Given that CDK2/cyclin E1 complex is dynamically active in S phase entry and that NF90 stabilizes cyclin E1 mRNA to accelerate S phase entrance, we postulated that CDK2 phosphorylated NF90 to affect cell cycle and tumor progression." (PMID 32123579, 2020). "Further, ST3Gal IV overexpression increased the Jagged1, Notch1, Hes1, Hey1 and p21 expression, meanwhile, decreased the expression levels of CyclinD1, CyclinE1, CDK2 and CDK4 in xenograft tumor tissues." (PMID 33598419, 2020). "Xylocydine, a CDK2 specific inhibitor that selectively down-regulates CDK2 activity, had significant growth inhibitory effects in HCC cells in vitro, as well as suppressed tumor growth in vivo in murine xenografts." (PMID 32018226, 2020). "CDKN1A is a tumor suppressor that mainly functions as a cell cycle checkpoint by binding to CDK1, Cyclin‐dependent kinase 2 (CDK2), or the CDK4/6 complex." (PMID 33037696, 2020). "Among the potential drug targets, we identified some well-known targets, including EGFR, ERBB2, and PARP1 as well as CDK2 and CDK4/6, which are related to the regulation of tumor cells development." (PMID 33287876, 2020). "Notable interactions between CCNA1 and CDK1 and CCNA1 and CDK2 demonstrate the contribution of CCNA1 in the progression of cell proliferation and tumor growth, but only when involved with the kinases." (PMID 33182737, 2020). "Roniciclib binds to and inhibits the activity of CDK1/Cyclin B, CDK2/Cyclin E, CDK4/Cyclin D1, CDK6/Cyclin D3, and CDK9/Cyclin T1, which are serine/threonine kinases playing key roles in the regulation of tumor cell proliferation and survival." (PMID 32737364, 2020). "Furthermore, the combination of either CDK2 or EZH2 inhibitor with tamoxifen effectively suppresses tumor growth and markedly improves the survival of the mice bearing TNBC tumors, suggesting that the mechanism-based combination therapy may be an alternative approach to treat TNBC." (PMID 31704972, 2019).
tumor (continued). "The PI3K/AKT pathway is closely related to the proliferation, differentiation, apoptosis, migration, and adhesion of tumor cells involving multiple targets, including EGFR, BCL2, GSK3B, CDK2, and CDK4." (PMID 31406500, 2019). "Eight miRNA-449-family target genes (CDC25A, SIRT1, GMNN, E2F1, E2F3, BCL2, CDK2, and CCNE2) were selected; all of them involved in tumor development, cell cycle, and apoptosis." (PMID 30926829, 2019). "Our data validate MET/FAK signalling as a mechanism that enables CDK4/6-independent CDK2 activation and cell cycle transit, and we provide evidence for the utility of MET or FAK inhibition as a means to improve tumour response to CDK4/6 inhibition in vivo." (PMID 31296956, 2019). "In consistent with the in vitro results, immunoblotting analysis of tumor homogenates showed that miR-141 mimics induced upregulation of p27 and E-cadherin, and downregulation of NRP-1, CDK2, cyclin E, Snail and N-cadherin." (PMID 31572065, 2019). "We also observed possible evidence of cell cycle targeting via CDK2, as cyclin E was downregulated in the brains of CYC065-treated tumor-bearing animals." (PMID 31842413, 2019). "In mice tumor tissue, phosphorylation of Src and ERK1/2 and expression of CDK2 were significantly decreased in EP-treated groups." (PMID 30988279, 2019). "(iv) PPM1A was a member of the protein phosphatase 2C family and an important tumor suppressor, which was involved in regulation of multiple pathways, such as TGFβ/Smad, JNK/p38, Cdk2, Cdk6, and Akt/ERK signaling." (PMID 31920959, 2019). "Nevertheless, these finding provided the rationale for the development of therapeutic approach that specifically exploit the tumor dependence upon CCNE1 amplification, for instance by targeting CDK2 and AKT activities." (PMID 31491988, 2019). "In conformity with previous findings, our studies also indicate that inhibition of cyclin D1, CCRK and CDK2 are involved in inhibition of growth and proliferation in EMCA cells and tumor regression in mice." (PMID 30846786, 2019). "A mass of studies have demonstrated that PPARγ agonists via inhibiting the expression of cyclinD1, cyclinB, cyclinE, CDK4 and CDK2 and increasing the expression of CDKN1A to prevent cell cycle from G1 to S phase to prohibit tumor cells proliferation." (PMID 29642873, 2018). "miR-320a-PBX3 inhibits the active pathway of the MAPK and EMT and reduces the expression of dependent cytokinase 2 (CDK2) and MMP2 to inhibit tumor development." (PMID 29552328, 2018). "CDK family members, such as CDK2, CDK4, and CDK6, play a key role in the cell-cycle control of tumor cells." (PMID 29370087, 2018). "E diet with PS administration presented the lowest CDK2, phospho-AKT, and phospho-ERK expression levels compared with those of the other tumor groups." (PMID 29435127, 2018). "Among the overlapping genes, we extracted CDK2, CDK6, and EGFR, which are all known to promote tumor cell growth." (PMID 29540837, 2018). "PLAC2 suppressed tumour cell proliferation in an RPL36‐dependent manner and induced cell cycle arrest via down‐regulation of CDK2." (PMID 28922548, 2018). "Western blotting of the xenograft tumour tissues from the nude mouse model showed that overexpression of ABHD11‐AS1 increased the expression of cyclin D1, CDK1, CDK2, CDK4, Bcl‐xl and VEGFA and decreased the expression of p16." (PMID 29799152, 2018). "Cyclin-dependent kinase 2 (Cdk2) is a key cell cycle regulator, with roles in inactivating phosphorylation of the RB1 (pRb) tumour suppressor family and in controlling both G1/S and G2/M transitions." (PMID 29044141, 2017). "The strongest prognostic power (P = 0.0024 and 0.00065) came from the gene-set pair of two ENSC markers (CDK2 and CDKN344) with two NB tumour suppressors (CDKN1B and CDKN2D45, 46)." (PMID 28246384, 2017). "c-Myc plays a essential role in this Roniciclib-impacting ESC-like signature, which is evident by the occupancy of c-Myc at both the CDK2 and CCND1 promoters in tumor." (PMID 28246384, 2017).
tumor (continued). "Consistently, dinaciclib blocked CDK2 and CDK9 activity by abolishing the phosphorylation of Rb (Ser807/811) and RNAP II (Ser2) and ultimately induced PARP cleavage in those tumor tissues." (PMID 27378523, 2016). "The IHC analysis results revealed that the number of lipid vacuoles and the expression of PCNA, Ki67, CDK2, and CDK4 were significantly greater in tumor tissues obtained from the mice fed on the HFD as compared to those of CD-fed mice." (PMID 25912035, 2015). "As expected, there was a down regulation of cellular proliferation molecules CDK1, CDK2, CDK4, CDK6, Cyclin D1, Cyclin E and Cyclin B1 and upregulation of p16 and p21 in the xenograft tumor tissues by IHC." (PMID 26590805, 2015). "We therefore measured the effects of embelin on the expression of cell cycle proteins (Cyclin D1, CDK-2, and CDK-6), and Bcl-2 family members (Bcl-2, and Bax) in tumor tissues by Western blot analysis and immunohistochemistry." (PMID 24694877, 2014). "It has been reported that ATM can act as a tumor suppressor in liver cancer, by directly phosphorylating Tax1 binding protein 2 (TAX1BP2), a cyclin-dependent kinase 2-regulated tumor suppressor." (PMID 25247188, 2014). "The protein levels of Cyclin E1, Cyclin D3, Cyclin D1,Cyclin A2, CDK2 and CDK4 were significantly decreased in tumor tissues harvested from miR-188 injected mice." (PMID 25304455, 2014). "Since cdk2 and cyclin A were distinctly increased in RCCres and were mainly affected by VPA treatment, their functional relevance during resistance dependent tumor growth was evaluated by siRNA knock-down." (PMID 24935000, 2014). "In contrast, CDK2 and PCNA appeared to be up-regulated in all HCC tissues compared to non-tumor tissues." (PMID 22132221, 2011). "Thirty-nine tumours (43.3%) and 31 tumours (34.4%) exhibited both cytoplasmic and nuclear positivity for CDK4 and CDK2 respectively." (PMID 10390005, 1999). "Of 28 cyclin D1-positive and 27 cyclin E-positive tumours, CDK4 was overexpressed in 12 (42.8%) tumours and CDK2 in seven (25.9%) tumours respectively." (PMID 10390005, 1999). "In this study, the expression of the tumor-suppressive CDK inhibitor p27 was increased, and the expression of oncogenic CDK2 and CDK4; cyclins (A, D, and E); and pRb was decreased by galectin-1 knockdown and miR-22-3p overexpression in primary hormone receptor-positive breast cancer cells." (PMID 39996781, 2025). "Mechanistically, UNC13B may exert tumor-promoting effects by modulating key regulatory proteins, including PINK1, CDK2, AKR7A3, and Bim." (PMID 41007649, 2025). "Nevertheless, Dinaciclib, which is a selective CDK inhibitor targeting CDK1, CDK2, CDK5, and CDK9, appears to be insufficient in conclusively demonstrating the role of CDK2 in tumor immunogenicity and a role for the specific inhibition of CDKs in inducing ICD has not been described." (PMID 40557162, 2025). "In addition, CENtromere Protein A-mediated centromere activation of cyclin E1/CDK2 in conjunction with FBXW7 deletion to induce chromosomal instability and tumor growth." (PMID 41373479, 2025). "Therefore, NEK6 regulates CDK2 and Bcl-2 through YBX1, which synergizes with CDK4/6 inhibitors to inhibit tumor growth." (PMID 41560755, 2025). "CDK2 is not considered active in tumors, but the cyclinA-CDK2 complex is frequently overexpressed in tumor cells." (PMID 40486867, 2025). "QUE stimulated the level of cyclin D1 in normal cells, not in tumor cells, which increased the levels of cellular p21 and Cdk2." (PMID 39459023, 2024). "Furthermore, our research elucidated the tumor-promoting function of PI3K-AKT and CDK2-Rb activation, both of which can be suppressed by DNMT1-specific DNA hypomethylation." (PMID 38755637, 2024).
tumor (continued). "This study compared the expression levels of miR-4516, Wnt 8B, FZD2, DVL3, FOSL1, CDK1, CDK2, CCNA1, and CCNB1 in primary LUAD tumor tissue with those in normal lung tissue using data from The Cancer Genome Atlas (TCGA) database to assess the consistency of our findings with the human sample." (PMID 38930863, 2024). "CDK2 activated MYBL2 by phosphorylation, leading to anti-PD-1 resistance in OC, but the CDK2 inhibitor CVT-313 suppressed MYBL2 in A2780 and SKOV3 OC cells and circumvented anti-PD-1 resistance of murine ID8 OC by modulation of the tumor microenvironment." (PMID 38835346, 2024). "Mechanistically, we propose a functional model wherein DNMT1-remodeled genome-wide DNA hypomethylation patterns regulate oral malignant transformation and tumor growth, through signal collaborations involving PI3K-AKT, CDK2-Rb and GSK3β-mediated glycogen metabolism." (PMID 38755637, 2024). "Being a potent inhibitor of CDK2/CDK5, (S)-PHA533533 was developed as an anti-tumor drug and has been previously preclinically tested by administrating 7.5 mg/kg orally into a human ovarian A2780 xenograft mouse model twice a day for 20 days without any signs of toxicity." (PMID 38977672, 2024). "Moreover, the phosphorylation of the Rb protein decreased in the sh-DNMT1 group, further supporting our discovery that DNMT1-remodeled DNA hypomethylation can inhibit tumor growth by concurrently suppressing the PI3K-AKT and CDK2-Rb signaling pathways." (PMID 38755637, 2024). "Furthermore, the expression of the proliferation marker Ki67, and the cell cycle markers CDK2, CDK4, and CyclinD1 was analyzed through immunohistochemical detection of tumor samples." (PMID 38027998, 2023). "Moreover, like CDK2, CDK4/CDK6 exert oncogenic roles in this tumor type, especially in MYC-amplified forms." (PMID 36839989, 2023). "In addition, T-loop phosphorylation of CDK1/CDK2 was additively decreased by CT7001 and enzalutamide treatments, and a decrease in PolII phosphorylation was detected in tumours treated with CT7001 alone or in combination with enzalutamide." (PMID 37076563, 2023). "Furthermore, the expression levels of RAC1, CDK2, RUVBL2, and MET were upregulated in the tumor group compared to the control group and showed a noticeably positive correlation with the expression level of RHOA." (PMID 35406376, 2022). "CDKN1B protein is thought to be a tumor suppressor with a haploid phenotype, and CDK2 activity is increased in the absence of p27." (PMID 35126159, 2022). "Our study supports the clinical development of therapeutic strategies co-targeting ER, CDK4/6 and CDK2 following progression on AI-monotherapy or combined CDK4/6i and ET to improve survival of patients exhibiting high tumor levels of CDK6, p-CDK2, and/or cyclin E1." (PMID 36153348, 2022). "Importantly, combination of CDK2 inhibitor (K03861) and PTX, the first-line drug of TNBC, resulted in synergistic tumor growth inhibition of TNBC cells." (PMID 33541412, 2021). "Finally, we performed HE staining, immunofluorescence staining, immunohistochemical staining, and Western blot analysis on nude mouse tumor tissues to detect protein expression changes in HK2, GLUT1, Ki67, PCNA, CDK2, CyclinD1, Bax, and Bcl-2." (PMID 34893086, 2021).